DCAF12L2 (DDB1 and CUL4 associated factor 12 like 2)
Synonyms: WDR40C
Tractability: No criterion of Open Targets' tractability assessment is met for any kind of drug.
Gene: Protein-coding gene on chromosome X (126,163,499 to 126,166,289, reverse strand). Ensembl gene ENSG00000198354.
Subcellular location (Human Protein Atlas): Cytosol
Gene Ontology:
Cellular component: Cul4-RING E3 ubiquitin ligase complex
Homologues: Orthologues: chimpanzee DCAF12L2 (99% identical), macaque DCAF12L2 (99% identical), pig DCAF12L2 (89% identical), mouse Dcaf12l2 (82% identical), rat Dcaf12l2 (82% identical), mouse Dcaf12l1 (77% identical), rat Dcaf12l1 (77% identical), guinea pig DCAF12L2 (70% identical). Paralogues in human: DCAF12L1 (87% identical), DCAF12 (64% identical).
Diseases named in the same sentence as DCAF12L2 in open-access papers:
DCAF12L2 is named in the same sentence as 3 diseases in open-access papers, as found by Europe PMC text mining. Sharing a sentence is not in itself a finding about the gene and the disease. The quoted sentences say what the papers report.
Global developmental delay (1 paper, 2021). A delay in the achievement of motor or mental milestones in the domains of development of a child, including motor skills, speech and language, cognitive skills, and social and emotional skills. "DCAF12L2 is located in a region with several reported deletions and duplications in patients with intellectual disability (ID), global developmental delay (GDD), and delayed speech and language development, as well as seizures." (PMID 34069769, 2021).
cancer (1 paper, 2020). A tumor composed of atypical neoplastic, often pleomorphic cells that invade other tissues. "The second transcript was linked to the gene DCAF12L2, which was shown to be mutated in several human cancers." (PMID 32821278, 2020). "These eight transcripts were linked to the following cancer‐related genes: TRIM33, USP6, PRDM16, SETD1B, MLLT3, KEAP1, CHD2, and DCAF12L2." (PMID 32821278, 2020).
DCAF12L2 also shares sentences with these, for which no sentence is quoted: Intellectual disability (1 paper).